PALB2 (partner and localizer of BRCA2)
Diseases named in the same sentence as PALB2 in open-access papers (continued):
Sharing a sentence is not in itself a finding about the gene and the disease.
breast cancer (continued). "This year, however, a study including 15,104 prospectively followed women treated with ipsilateral surgery for invasive breast cancer reported a 35% 10-year cumulative incidence of contralateral breast cancer for PALB2 truncating variant carriers with ER-negative breast cancer." (PMID 37686625, 2023). "We have reported the prognosis of breast cancer associated with a PALB2 mutation to be poor." (PMID 37510234, 2023). "Furthermore, recently published studies confirmed the activity of PARP-i also in breast cancer patients with other germline mutated genes such as PALB2." (PMID 37174000, 2023). "PALB2 should be included on a breast cancer predisposition gene panel." (PMID 36411032, 2023). "Notably, each of these variants is unique to a single patient, and 2 patients were carriers for two variants each: Patient H3168 had stop gain variants in FANCA and PALB2, and had a sister with lung cancer, and another sister with breast cancer." (PMID 37461096, 2023). "In patients with pancreatic, ovarian, prostate, and breast cancers harboring PALB2 mutations, the clinical benefit of receiving PARPis is observed in various studies, especially in those using approaches similar to the one typically seen for BRCA-altered tumors." (PMID 37761329, 2023). "Thus, even though the frequency of mutations in the PALB2 gene is rare (from 0.1% to 2.7%), the risk of developing breast cancer, at least for some PALB2 mutations, remains high." (PMID 37628606, 2023). "Germline testing for breast cancer should also include the PALB2 gene, considering the frequency of pathogenic defects in the general population and because PALB2 heterozygotes should be considered for the same therapeutic regimens and clinical trials as those for BRCA1 and BRCA2 carriers." (PMID 37239058, 2023). "Recently published studies assessing the clinical validity of genes frequently tested in hereditary breast and ovarian cancer mostly agree that ATM, BRCA1, BRCA2, CHEK2, and PALB2 are strongly associated with a risk of breast cancer (overall with a p value of less than 0.0001)." (PMID 37239898, 2023). "In BRCA1/2− breast cancer, PALB2 germline variants were the most prevalent." (PMID 38114467, 2023). "However, among cases with a family history of breast cancer, PTVs in PALB2 were significantly associated with a high risk of disease (p < 0.05), a finding consistent with reported associations." (PMID 37790698, 2023). "In conclusion, our study reported a cohort of Taiwanese breast cancers harboring mutations in BRCA1, BRCA2, and PALB2 through tumor-only sequencing, which underscores the impact of BRCA1/2 and PALB2 on breast cancer risk and potential therapeutic opportunities." (PMID 38098088, 2023). "Previously, we have identified pathogenic mutations of BRCA1, BRCA2, CHEK2, and PALB2 in about half of 1018 Polish families with hereditary breast cancer, and we have observed that 18 founder mutations are responsible for about 80% of all the mutations detected in these genes." (PMID 37510234, 2023). "This retrospective study demonstrated that the reversion mutations were observed in three HRR-associated genes (BRCA1, BRCA2 and PALB2) with four cancer types (breast cancer, pancreatic cancer, ovarian cancer, and lung cancer) from this Chinese pan-cancer patient cohort." (PMID 35281878, 2022). "However, more studies are needed to confirm the importance of PALB2 mutations on the age of onset of breast cancer." (PMID 36685821, 2022). "EARS2 expression might be a risk factor for pancreatic cancer in breast cancer patients with PALB2 mutations." (PMID 35779338, 2022). "In the current study, we originally aimed to co-delete Palb2 and Atg7 in the mammary gland using Cre recombinase driven by the promoter of whey acidic protein (Wap-Cre), to further study the role of autophagy in PALB2-associated breast cancer." (PMID 35404932, 2022). "PALB2 pathogenic variants confer high risk of breast cancer." (PMID 36139699, 2022).
breast cancer (continued). "In a recently published study, we described a genetic interaction and functional cooperation between Atg7, an essential autophagy gene, and Palb2, a breast cancer susceptibility gene, in the maintenance of mitochondrial function, redox homeostasis, and neuronal viability." (PMID 40396054, 2022). "In addition to being detected in breast cancer at a somatic level, note that the PALB2 gene is considered a high-risk breast cancer gene if mutated at a germline level." (PMID 36278678, 2022). "In this study, we evaluated the impact of breast cancer patient-derived VUSs on PALB2 function and aimed to identify pathogenic PALB2 missense variants that may increase cancer risk." (PMID 35853885, 2022). "In conclusion, EARS2 expression might be a risk factor for pancreatic cancer in breast cancer patients with PALB2 mutations." (PMID 35779338, 2022). "However, a major challenge for genetic risk assessment is to quantify the relationship between PALB2 function deficiency and increased breast cancer risk." (PMID 35853885, 2022). "Interestingly, impaired autophagy, due to monoallelic loss of the essential autophagy gene Becn1, delayed and reduced Palb2-associated mammary tumorigenesis, suggesting that autophagy facilitates mammary tumor development following the loss of PALB2." (PMID 35404932, 2022). "The sensitivity of HRDetect for predicting BRCA1/2 mutation in the validation cohort was 86% in ER+/HER2- breast cancer patients and showed sensitivity to detect PALB2 biallelic inactivation or RAD51C hypermethylation, and to reclassify BRCA1/2 VUS as germline PV." (PMID 35158866, 2022). "PALB2 reversion mutation was only detected from one case with breast cancer." (PMID 35281878, 2022). "Male breast cancer patients who carry a mutation in PALB2 gene may be candidates for screening for second primary malignancies." (PMID 34461861, 2021). "Two previous studies reported an association of PALB2 mutations and breast cancer risk in men." (PMID 34461861, 2021). "Similarly, the c.1027C>T (p.Gln343*) PV in the breast cancer predisposition gene PALB2, was identified in familial breast cancer cases from BGP with a carrier frequency of 5.3% and located in a conserved haplotype." (PMID 33573335, 2021). "The case with PALB2 germline mutation has a family history of breast cancer." (PMID 34007008, 2021). "In addition, patients with PALB2 mutation should be offered breast cancer surveillance similar to that for BRCA1/2 carriers." (PMID 34439348, 2021). "However, in later studies, penetrance of variants of PALB2 in breast cancer development was found to be distinctively varied in different populations." (PMID 35008774, 2021). "Breast cancer-related mutations of PALB2 cause only minor attenuation of the binding affinity." (PMID 34946951, 2021). "Inherited mutations in BRCA1, BRCA2, and PALB2 cause a high risk of breast cancer." (PMID 33893322, 2021). "Moreover, PALB2 mutations accounted for 1.1% of the breast cancer cases in the Caucasian population." (PMID 34439348, 2021). "Similarly, studies showed that PALB2 mutations account for approximately 1–2% of early onset breast cancer patients in the Chinese population." (PMID 34439348, 2021). "Thus, the cumulative breast cancer risk for female carriers of PALB2 variants is 14% by the age of 50 years and up to 35% in women above the age of 70." (PMID 33718150, 2021). "The PALB2 gene was recently classified as a high risk breast cancer susceptibility gene in Caucasian women, with 53% cumulative risk to age 80 years and 7-fold relative risk for female breast cancer, which was comparable to the breast cancer risk of the BRCA2 gene in Caucasian women." (PMID 34606182, 2021).
breast cancer (continued). "All trials that explore the efficacy of PARPi in high-penetrance risk genes (BRCA1/2, PALB2) have shown activity in those genes, definitely introducing in the metastatic breast cancer therapeutic algorithm a new standard treatment for germline mutation carriers." (PMID 33800556, 2021). "A previous study reported that PALB2 is a breast-cancer-susceptibility gene." (PMID 34567566, 2021). "In our cohort, 3 of 4 men with breast cancer and a PALB2 mutation died of metastatic cancer." (PMID 34461861, 2021). "The PALB2 variant therefore, may have contributed to the breast cancer occurring in the mother (tumour tissue was unavailable for further analysis) but not the wtGISTs in this family." (PMID 33854214, 2021). "We identified a strong association with PALB2 mutation and male breast cancer (OR = 11.6)." (PMID 34461861, 2021). "PALB2 was believed to contribute moderately to breast cancer risk previously." (PMID 34439348, 2021). "PALB2 is a breast cancer predisposition gene and this is a frequently identified variant with >10 ClinVar entries with pathogenic assertion, mostly with reference to breast cancer predisposition." (PMID 33854214, 2021). "Although DNA was not available from the EC-affected mother, the pedigree analysis indicates she is an obligate carrier; genotyping of three other relatives identified two carrying the PALB2 variant, specifically a sister with colon cancer and maternal cousin with breast cancer." (PMID 33917078, 2021). "Besides, PALB2 expression in CTCs was already described and linked with worse outcome in advanced breast cancer patients by our group." (PMID 34071445, 2021). "The identified PALB2 p.A1079S variant is located within a highly relevant functional domain, in close proximity to the breast cancer‐associated functional missense mutations p.L939W, p.T1030I and p.L1143P and likewise shows increased cellular sensitivity to ionizing radiation." (PMID 34382369, 2021). "Thus, understanding the cancer risk and phenotypic presentations of the PALB2 mutation in Chinese breast cancer contribute to clinical management decisions." (PMID 34439348, 2021). "In the SEER database, PALB2 mutations are among the prevalent pathogenic variants in breast cancer." (PMID 33193564, 2020). "Moreover, women carrying pathogenetic variants of PALB2 have a 35% lifetime risk to develop breast cancer by 70 years of age." (PMID 32733558, 2020). "While the elevated PRS distribution followed the breast cancer incidence distribution with highest rates in the early-settlement region in South-Western Finland, the allele frequencies for the PALB2 and CHEK2 mutations were highest in the late-settlement region in Eastern Finland." (PMID 33318493, 2020). "Moreover, we describe the link between PALB2 pathogenic variants (PVs) and breast cancer predisposition, aggressive clinicopathological features, and adverse clinical prognosis." (PMID 32185139, 2020). "Thus, germline PALB2 status is crucial for breast cancer risk assessment in individuals with an apparent family history of breast cancer." (PMID 32185139, 2020). "PALB2 is also reported as one of the breast cancer susceptibility genes." (PMID 32703994, 2020). "In addition to breast cancer, PALB2 has also been identified as a susceptibility gene for pancreatic cancer." (PMID 32185139, 2020). "Among 3,090 patients with breast cancer in the cBioPortal database, only 25 (25/3,090) had somatic PALB2 mutations; 20 were missense mutations and five were high-risk mutations, including four stop-gain mutations (E12∗, E667∗, Q1146∗, and Q822∗) and one frameshift mutation (I1035Mfs∗6)." (PMID 33193564, 2020). "Ethnic-specific PALB2 recurrent mutations and related breast cancer predisposition." (PMID 32185139, 2020). "The PALB2 gene is considered a high-risk gene for hereditary breast cancer." (PMID 33134171, 2020). "The life-time risk of breast cancer for PALB2 normal population is 12.4% for females." (PMID 33193564, 2020).
breast cancer (continued). "Here, we sought to define the repertoire of somatic genetic alterations in PALB2-associated breast cancers (BCs), and whether PALB2-associated BCs display bi-allelic inactivation of PALB2 and/or genomic features of HR-deficiency (HRD)." (PMID 31428676, 2019). "Unsurprisingly, PALB2 truncating mutations have been tied to increased risks of developing the disease with lifetime risks of breast cancer of 24–54%, depending on family history of breast cancer." (PMID 31586400, 2019). "Among the 16 PALB2-associated breast cancers analyzed by WES, the 12 cases with bi-allelic PALB2 inactivation harbored a numerically higher somatic mutation rate (median 139.5, range 63–269) than the four cases without bi-allelic inactivation (median 103, range 59–109; P = 0.09)." (PMID 31428676, 2019). "In agreement with previous studies showing that most breast cancers with HRD features are underpinned by bi-allelic inactivation of HR-related genes, we identified the genetic basis of HRD in 12 out of 14 (86%) PALB2-associated breast cancers with genomic features of HRD." (PMID 31428676, 2019). "Finally, the fourth patient with another pathogenic nonsense variant, c.2218C>T (p.Gln740*), in PALB2 was a woman who had been diagnosed with breast cancer at age 48 years." (PMID 31125277, 2019). "One could hypothesize that these cases could correspond to sporadic breast cancers arising in PALB2 germline mutation carriers, in which the second PALB2 allele was inactivated later in tumor evolution." (PMID 31428676, 2019). "Bi-allelic PALB2 inactivation was found in 16 of the 24 PALB2-associated breast cancers (67%)." (PMID 31428676, 2019). "The higher rate of PALB2 mutations indicates the high risk of breast cancer in the carriers." (PMID 30975222, 2019). "However, PALB2 has been recently emerged to be a moderate-penetrant gene for breast cancer susceptibility." (PMID 30975222, 2019). "As part of the exploratory analysis, we investigated whether PALB2-associated breast cancers would differ from non-BRCA1/2/PALB2-associated breast cancers in regard to the frequencies of genomic features indicative of HRD." (PMID 31428676, 2019). "Importantly, however, these analyses revealed that PALB2-associated breast cancers with bi-allelic inactivation differ from non-BRCA1/2/PALB2-associated breast cancers but are similar to BRCA1 and BRCA2 breast cancers with bi-allelic inactivation." (PMID 31428676, 2019). "This has already led to the identification of numerous variants in PALB2, which may associate with breast cancer (as of September 2019, 1301 PALB2 VUS have already been reported in ClinVar)." (PMID 31757951, 2019). "Gene mutation in PALB2 increases breast cancer risk about twofold." (PMID 30975222, 2019). "In this context, one could posit that this subset of PALB2-associated breast cancers may retain competent HR repair of DNA double-strand breaks and would unlikely benefit from HRD-directed therapies." (PMID 31428676, 2019). "However, germline and somatic mutations of PALB2 are rare in breast cancer patients, varying from 0.1% to 2.7% depending on the population." (PMID 29321957, 2018). "PALB2 is another gene mutation associated with hereditary breast cancer." (PMID 30174725, 2018). "Furthermore, deletion of mouse Palb2, another breast cancer susceptibility gene with functional similarities to BRCA1, does not rescue Cobra1 knockout-associated mammary defects." (PMID 29426838, 2018).
breast cancer (continued). "In addition, for the 71 breast cancer patients with nearby lymph nodes involved (N1, N2 or N3), high PALB2 score (IHC score ≥ 1.5) was significantly associated with poorer overall survival (P = 0.002) as suggested by the log‐rank test." (PMID 29321957, 2018). "The high expression of PALB2 may potentially promote the function of BRCA2 to cause or enhance the progress of breast cancer." (PMID 29321957, 2018). "In addition to BRCA1/2, genes with an established role in breast cancer, other predisposing genes such as CHEK and PALB2 were evaluated for a possible association with the risk of breast cancer, although their frequency and penetrance was significantly lower." (PMID 29093764, 2017). "However, seven independent studies reported PALB2 S417Y as a germline mutation in both cancer patients (mainly breast cancer) and healthy individuals, making this variant the most frequent of the subset we analysed." (PMID 29387807, 2017). "Females with monoallelic germline loss of PALB2 have a 2–4 fold increased breast cancer risk." (PMID 28591191, 2017). "As PALB2 links BRCA1 and BRCA2 and mutations in this gene is associated to susceptibility to breast cancer, it became a natural question whether PALB2 mutations could also lead to OC." (PMID 28858227, 2017). "For European women, strong evidence of association with breast cancer risk was observed for PALB2 c.1592delT OR 3.44 (95% CI 1.39 to 8.52, p=7.1×10−5), PALB2 c.3113G>A OR 4.21 (95% CI 1.84 to 9.60, p=6.9×10−8) and ATM c.7271T>G OR 11.0 (95% CI 1.42 to 85.7, p=0.0012)." (PMID 27595995, 2016). "Similarly, an Australian population-based case–control-family study of breast cancer estimated the cumulative risk for PALB2 c.3113G > A to be 91 % (95 % CI, 44–100 %) to the age of 70 years." (PMID 27099641, 2016). "Thus, all published estimates of penetrance of PALB2 mutations are comparable to the breast cancer risk associated with BRCA2 mutations: 45 % (95 % CI, 31–56 %)." (PMID 27099641, 2016). "PALB2 has taken its place with bona fide breast cancer susceptibility genes." (PMID 27099641, 2016). "In our study, 152 specimen of patients with hereditary predisposition to breast cancer (including patients with early-onset breast cancer, family history of breast or ovarian cancer, bilateral cancer, or male breast cancer) were studied for PALB2 mutations." (PMID 26489409, 2015). "In this study, we performed germline mutation analysis of the entire coding region of PALB2 in a cohort of 1996 breast cancer index cases referred to familial cancer clinics for genetic testing and tested negative for BRCA1 and BRCA2 mutations as well as 1998 Australian cancer-free female controls." (PMID 26283626, 2015). "To date, only a very limited number of studies have focused on the association between PALB2 mutations and hereditary predisposition to breast cancer in China, and ethnic Han Chinese patients were enrolled in most of these studies, with no study addressing multiple ethnic groups in China." (PMID 26489409, 2015). "Truncating PALB2 heterozygous mutations have been identified in bilateral breast cancer patients." (PMID 26489409, 2015). "Our findings support truncating variants in PALB2 as high-penetrance breast cancer susceptibility alleles, and suggest that a common missense variant may also lead to a low level of increased breast cancer risk." (PMID 26283626, 2015). "For this purpose, we sequenced the complete coding and flanking regulatory regions of PALB2 from constitutional DNA of 152 patients with hereditary predisposition to breast cancer, all previously employed to study the distribution of germline mutations in BRCA1, BRCA2." (PMID 26489409, 2015).